ERG (ETS transcription factor ERG)
Diseases named in the same sentence as ERG in open-access papers (continued):
Sharing a sentence is not in itself a finding about the gene and the disease.
prostate carcinoma (continued). "The aim of this study was to investigate the expression of two commonly altered genes ERG and PTEN in prostate cancer (PC) and evaluate their prognostic significance." (PMID 25897494, 2015). "One such example, found in 50 % of prostate cancers, involves the fusion between the ETS transcription factor ERG with the androgen-regulated gene TMPRSS2, resulting in overexpression of ERG in the prostate epithelium." (PMID 26310325, 2015). "ETS family gene fusions, primarily including ERG (and less frequently, ETV1, ETV4, ETV5 or FLI1), are found in approximately 50 % of prostate cancers, the most common fusion being TMPRSS2-ERG." (PMID 26684754, 2015). "In prostate cancer cells USP9X has been found to deubiquitinate and stabilise ERG, while increasing expression of USP9X was found to correlate with higher grade and poorer outcome in oesophageal squamous cell carcinomas." (PMID 26506417, 2015). "For example, the most studied fusion in prostate cancer is formed between the TMPRSS2 and ERG genes, resulting in ERG transcription being driven by the androgen-responsive TMPRSS2 promoter." (PMID 26626734, 2015). "ERG, a member of the ETS oncogene family, is intimately involved in the development of multiple cancers including prostate cancer." (PMID 26035298, 2015). "We recently reported mouse models of prostate cancer that recapitulate the most frequent ETS gene fusions, TMPRSS2-ERG and TMPRSS2-ETV1, with ectopic ERG or ETV1 expression from the endogenous Tmprss2 promoter." (PMID 25780911, 2015). "The results of this analysis represent a case for the use of the ratio of Type I/Type II ERG, in conjunction with C-MYC gene expression levels, to serve as potential prognostic markers for treatment of prostate cancer patients." (PMID 25221645, 2014). "Using fluorescence in situ hybridization (FISH) and immunohistochemistry, we evaluated ERG, PTEN and EGFR family aberrations in a cohort of 224 Chinese prostate cancer patients diagnosed in transurethral resection of the prostate (TUR-P)." (PMID 24516518, 2014). "The two most common genomic aberrations in prostate cancer are PTEN deletion and the TMPRSS2/ERG rearrangement." (PMID 24642271, 2014). "Chromosomal aberrations harboring a fusion product of ERG to form FUS/TLS-ERG in acute myeloid leukemia (AML), ERG-EWS in Ewing's sarcoma, or TMPRSS2-ERG in prostate cancers are predictive of poor prognosis." (PMID 24504051, 2014). "The fusion between ERG coding sequences and the TMPRSS2 promoter is the most prevalent in prostate cancer (CaP)." (PMID 25221645, 2014). "We recently reported that YK-4-279, an inhibitor of EWS-FLI1 oncoprotein in Ewings sarcoma, also inhibits ERG and ETV1 activity in prostate cancer cells in-vitro, resulting in reduced migratory and invasive phenotypes." (PMID 25479232, 2014). "Fitting together the scattered pieces of this jigsaw puzzle indicates that the disturbance of miRNA mediated regulation of ERG and EZH2 in prostate cancer requires detailed investigation." (PMID 24739220, 2014). "There is evidence for an oncogenic role of ERG and the other ETS transcription factors in many human cancers, including sarcomas, prostate cancer, and acute myeloid leukemia, in most cases via chromosomal translocations." (PMID 25239601, 2014). "Constitutive activation of ERG, ETV4, or ETV5 following gene fusion with the TMPRSS2 promoter renders the fusion gene oncogenic in prostate cancer cells." (PMID 24624361, 2014). "About 90% of gene fusions in prostate cancer are accounted by the fusion between the transmembrane protease, serine 2 (TMPRSS2), that is a strong androgen-regulated gene and the ERG gene, a v-ets erythroblastosis virus E26 oncogene homolog (avian)." (PMID 26317031, 2014). "ERG target genes such as calcium channel, voltage-dependent, L type, α-1D subunit (CACNA1D) were significantly upregulated in TMPRSS2-ERG positive prostate cancer cells." (PMID 24739220, 2014).
prostate carcinoma (continued). "A similar relationship was observed with ERG expression and methylation status of its target gene namely TDRD1 in prostate cancer." (PMID 24664224, 2014). "Recently, it has been shown that ETS factors such as ERG markedly increase AR binding in mouse prostate tissue and mediate robust transcriptional changes in PTEN null prostate cancer cells." (PMID 24737870, 2014). "Recently, ETS-related gene (ERG) gene rearrangements, phosphatase tensin homologue (PTEN) deletions and EGFR family aberrations were characterized as potential biomarkers for prostate cancer (PCa) patient management." (PMID 24516518, 2014). "In general, ERG-rearrangement positive cases contained DNA breakpoints located near AR binding sites, whereas ETS-negative prostate cancers harbored breakpoints significantly distant from AR binding sites." (PMID 25277175, 2014). "Translocations involving ERG and ETV1 constitute the majority of ETS rearrangements found in prostate cancer." (PMID 25479232, 2014). "As EWS–FLI1 includes the FLI1 Ets portion and some upstream regions, both RHA and YK-4-279 potentially directly bind the Ets domain, particularly as YK-4-279 also inhibits ERG and ETV1-mediated invasion in prostate cancer." (PMID 24450640, 2014). "Using this approach, it was reported that the inhibitor of the EWS-FLI1 oncoprotein in Ewing’s Sarcoma (YK-4-279) can downregulate the gene expressions of ERG and ETV1 downstream target genes in ETV1 or ERG fusion-positive prostate cancer cells." (PMID 24739220, 2014). "ERG is a member of the ETS family and a number of studies have investigated its role in prostate cancer." (PMID 24573402, 2014). "The fusion of the TMPRSS2 gene with E-twenty six (ETS) family genes like ETV1, ERG and ETV4 occurs in up to 70% of all prostate cancers and is therefore a specific biomarker for prostate cancer diagnostics." (PMID 23341502, 2013). "TMPRSS2/ERG rearrangement, PTEN gene deletion, and androgen receptor (AR) gene amplification have been observed in various stages of human prostate cancer." (PMID 24098661, 2013). "While the TMPRSS2:ETV1 fusion is rare and occurs in 1–10% of prostate cancers, the TMPRSS2:ERG fusion is present in roughly half of prostate cancers and is the most common genetic aberration so far described in prostate cancer." (PMID 23957008, 2013). "Six target genes were subjected to protein validation: GPR116, NPY and PLA2G7, three genes over-expressed in ERG+ tissues, and AZGP1, HPGD and TFF3, three genes down-regulated in ERG+ prostate cancer tissues." (PMID 23390522, 2013). "ERG, a member of the ETS transcription factor family, is frequently overexpressed in prostate cancer as a result of its fusion to the androgen-responsive Tmprss2 gene." (PMID 23472063, 2013). "ERG, an ETS family transcription factor, is known to be expressed in endothelial cells, and oncogenic ERG gene fusions occur in subsets of prostatic carcinoma, acute myeloid leukemia, and Ewing sarcoma." (PMID 23607024, 2013). "ERG is perhaps best known for the gene fusion product, TMPSSR2-ERG, which is common in approximately 50% of prostate cancers." (PMID 24175302, 2013). "We thus propose that overexpression of TDRD1, observed by us and others in 100% of TMPRSS2:ERG-positive prostate tumors, makes TDRD1 a promising target for immunotherapy of ERG rearrangement-positive prostate cancer." (PMID 23555854, 2013). "In prostate cancer, fusion of ETS-related genes (in most cases, the ERG) with AR-regulated gene promoter of TMPRSS2 is present in approximately 50% of prostate tumors." (PMID 23466879, 2013). "ERG and ETV1: These two genes belong to the ETS transcription factors and have been found to be overexpressed in prostate cancer tissues." (PMID 24282788, 2013).
prostate carcinoma (continued). "Recurrent gene fusions involving several members of ETS transcription factor family (ERG, ETV1, ETV4 or ETV5) were found to be the most frequent genetic alterations in prostate cancer, which can be detected in as many as 50%–70% of prostate cancer samples." (PMID 23852643, 2013). "Here, we report that ERG and TDRD1 are co-expressed in human prostate cancers and we provide a mechanistic explanation for the observed co-expression." (PMID 23555854, 2013). "TMPRSS2/ERG fusion gene indirectly up-regulates ZEB2, a facilitator of the epithelial to mesenchymal transition (EMT), by binding to IL1R2 to increase prostate cancer tumorigenesis." (PMID 24359571, 2013). "FLI1 and ERG, the major ETS transcription factors involved in rearrangements in the Ewing’s sarcoma family of tumors (ESFT) and in prostate carcinomas (PCa), respectively, belong to the same subfamily, having 98% sequence identity in the DNA binding domain." (PMID 23185447, 2012). "Recent experiments from our group have also indicated that YK-4-279 is able to inhibit ERG and ETV1 fusion-positive prostate cancer cell lines, and the activity and function of the enantiomers should be further investigated in prostate cancer." (PMID 22383402, 2012). "AMACR has been utilized in a panel of biomarkers including ERG, GOLPH2 and others to definitively detect early prostate cancer." (PMID 22641253, 2012). "These aggressive prostate cancers fuse the promoter of TMPRSS2, an androgen responsive gene, to an ETS family transcription factor, such as ETV1 or ERG, both of which have also been identified in joining to EWS in ESFT to form an oncogenic fusion protein." (PMID 22383402, 2012). "Prostate cancer derived urine exosomes are shown to contain two known prostate cancer biomarkers, PCA-3 and TMPRSS2: ERG, showing the potential for diagnosis and monitoring cancer patient’s status." (PMID 25419445, 2012). "We also identified that salinomycin reduced the expression of prostate cancer oncogenes, MYC, AR and ERG, which are known to have antioxidative properties." (PMID 22215106, 2012). "One of the prostate cancer-specific chromosome translocation is the fusion of TMPRSS2 and ERG genes, which has been reported in 60–70% of prostate cancer tissues." (PMID 23272087, 2012). "Molecular studies using specific FISH probes on CTCs from advanced prostate cancer patients have noted gains in AR and MYC, losses in PTEN, and evidence for ERG gene rearrangement." (PMID 22373240, 2012). "The ERG gene is frequently translocated to the TMPRSS2 promoter region; the resulting TMPRSS2-ERG fusion protein is positively expressed in half of human prostate cancer cases." (PMID 22454635, 2012). "Following ERG, ETV1 is the most frequently overexpressed ETS gene in prostate cancer (∼10% of the tumors)." (PMID 21298110, 2011). "We then found a significant (p<0.01) correlation between ERG expression and PIM1 up-regulation in a prostate cancer dataset, further confirming the link between ERG and PIM1 in prostate cancer." (PMID 22140532, 2011). "Especially TMPRSS2 fuses with ERG and Ets family genes such as ETV1, ETV4 and ETV5 in prostate cancers." (PMID 21347291, 2011). "Other seminal plasma proteases with matrix-regulation activities include TMPRSS2 (the most common fusion partner of ERG), HPN and PSA, all previously shown to be up-regulated in prostate cancer." (PMID 21814574, 2011). "Studies found that approximately 50% of prostate cancers harbor TMPRSS2-ERG fusions, of which greater than 90% over-express ERG." (PMID 21731703, 2011). "In human prostate cancer, genomic alterations of ETS-related genes, principally ERG, often occur as fusions between an androgen receptor-regulated gene promoter of TMPRSS2 and ETS transcription factors and are detected in about 50% of tumors." (PMID 22110995, 2011). "ERG and ETV1 are overexpressed in prostate cancer, but they also fuse with TMPRSS2, which leads to tumor progression." (PMID 24213111, 2011).
prostate carcinoma (continued). "Gene fusions involving members of the ETS family of transcription factors, such as ERG, ETV1, ETV4 and ETV5, have been shown to occur in a high proportion of prostate carcinomas." (PMID 21814574, 2011). "AR plays a crucial role in prostate cancer progression and is known to regulate the TMPRSS2 promoter, which constitutes the regulatory part of the TMPRSS2/ERG fusion." (PMID 21747944, 2011). "CTCs were successfully enriched and detected in men with advanced prostate cancer using an immunomagnetic enrichment procedure coupled with amplified molecular assays for PSA, PCA3, and TMPRSS2:ERG gene fusion mRNAs." (PMID 20598135, 2010). "Collectively, these data indicated that both EZH2 and NKx3.1 mediated relevant effects of ERG and ESE3 in prostate cancer cells." (PMID 20479932, 2010). "Numerous studies have now confirmed that approximately 50% of prostate cancers harbor a recurrent fusion between TMPRSS2 and ERG or ETV1." (PMID 20964841, 2010). "One of these has been shown to be overexpressed in PCa-PCA-3 and the other is a product of a chromosomal rearrangement, which creates a common prostate cancer-specific product, the TMPRSS2:ERG fusion." (PMID 19401683, 2009). "As a proof-of-concept, we show the presence of two known prostate cancer biomarkers, PCA-3 and TMPRSS2:ERG the in exosomes isolated from urine of patients, showing the potential for diagnosis and monitoring cancer patients status." (PMID 19401683, 2009). "For prostate cancer sample P140, the expected TMPRSS2 exon 1:ERG exon 4 fusion gene was assigned a fusion score rank of 95 within the 10,297 fusion breakpoints (and number one within the 154 measured junctions of TMPRSS2:ERG)." (PMID 19152679, 2009). "It is possible that like the fusions between TMPRSS2 and ERG, ETV1, ETV4 and ETV5, other functionally identical fusions are involved in changes in gene expression and prostate cancer development but are yet to be discovered." (PMID 18694509, 2008). "Among prostate cancer patients treated with surgery, the expression of TMPRSS2:ERG fusion gene is a strong prognostic factor and is independent of grade, stage and PSA level." (PMID 17971772, 2007). "Taken together, the results of our study demonstrate that MTAP deficiency is exceedingly rare in prostate cancer, while high MTAP expression is a strong and independent marker for poor prognosis in ERG negative cancers." (PMID 40554389, 2025). "ERG and EZH2 interact physically, and this functional ERG-EZH2 interaction enhances ERG transcriptional activity, producing profound changes in the transcriptional activity of prostate epithelial cells and sustaining prostate cancer progression." (PMID 40332527, 2025). "Prostate epithelia do not normally express ERG, but it has been reported that ERG is overexpressed in a high proportion of prostate carcinomas as a result of a gene fusion with the androgen-driven promoter of the TMPRSS2 gene." (PMID 40190563, 2025). "If molecular changes characteristic of prostate cancer, such as structural alterations in the TMPRSS2 and ERG genes, can be identified, histopathological evaluation could be conducted independently." (PMID 40565112, 2025). "Prostate cancer characterised by PTEN loss and absence of ERG expression (ERG−/PTEN−) signifies a distinct molecular subtype with profound biological and therapeutic implications." (PMID 40165885, 2025). "The upregulation of Drosophila Ets21C in the AG in response to oncogenic signaling could be particularly significant, considering its homology to the human ERG gene and other ETS transcription factors, known for their involvement in prostate cancer." (PMID 40304035, 2025). "Our result is consistent with previous findings that support the independent development of ERG fusion–positive and –negative prostate cancer from the normal prostate gland." (PMID 39347576, 2024).
prostate carcinoma (continued). "sGCα1 and sGCβ1 expression was also shown to be specifically and directly regulated by transmembrane protease serine 2 (TMPRSS2):v-ets erythroblastosis virus E26 oncogene homolog (ERG), also known as TMPRSS2:ERG or T2E (TMPRSS2-ERG), in PCa prostate cancer cells." (PMID 39337539, 2024). "Prostate cancer from EA men often contains ERG fusion/ETS family fusions and SPINK1 mutations, which are not as commonly found in prostate cancer from AA men." (PMID 38566104, 2024). "Therefore, this study investigated the prevalence of the ERG expression and its relationship with preoperative PSA, Gleason score, and age of patients with prostate cancer in Southwestern Uganda." (PMID 38730435, 2024). "To date, there is no information about the prevalence of ERG expression among prostate cancer patients in Uganda despite the high mortality from the disease." (PMID 38730435, 2024). "The divergent expression patterns that we discovered likely contribute to the separation of ERG-positive and ERG-negative samples in prostate cancer, as well as the formation of branching events within the two main branches." (PMID 39347576, 2024). "It has been shown that high-5hmC is an adverse predictor for biochemical recurrence of ERG-negative prostate cancers and can function as a prognostic marker for PCa development." (PMID 39183332, 2024). "This reveals binding sites for several known prostate cancer regulatory TFs, including AR, ERG, ETS1 and FOXA1 in a putative enhancer region that does not belong to the set of GWAS SNPs." (PMID 37971305, 2024). "This supports the idea that there are key late events that occur in the evolution of prostate cancer, regardless of ERG fusion status, that drive disease progression to a malignant phenotype." (PMID 39347576, 2024). "It was determined that for an ETS-related gene (ERG)-negative castration-resistant prostate cancer patient, drug-target engagement was significantly enhanced in CTCs when compared to the effects on ERG-positive patients." (PMID 38607014, 2024). "Furthermore, knockdown of PABPC1 reduced the interaction between ERG and EWS in prostate cancer cells." (PMID 37956771, 2023). "ERG, an ETS-domain transcription factor, is overexpressed in many prostate cancers." (PMID 37973913, 2023). "In human prostate cancer, TMPRSS2::ERG (T2E) is the most commonly observed oncofusion." (PMID 37509339, 2023). "The concordance of both ERG and PTEN status between IDC-P and adjacent prostate cancer generally demonstrates good agreement, with reports indicating that this concordance may be present in up to 100% of cases." (PMID 38067216, 2023). "The independent association of decreased PSAP expression with adverse outcomes in ERG-negative prostate cancer makes PSAP measurement a candidate marker for inclusion in multiparameter prognostic panels." (PMID 37892063, 2023). "On the contrary, when IDCP was ERG-negative, the adjacent prostate cancer was also ERG-negative and displayed high-grade morphology." (PMID 37185705, 2023). "In the present study, we specifically targeted HDAC3 in prostate cancer cells, highlighting a potential role for the ERG-NCoR-HDAC3 pathway in nonhematologic malignancies characterized by altered ERG expression." (PMID 37735473, 2023). "Characteristically, high-grade carcinomas of Gleason grade patterns 4 and 5 were ERG-negative, whereas low-grade prostate carcinomas of Gleason grade pattern 3 were ERG-positive." (PMID 37185705, 2023). "AMACR, an isomerase with enriched expression in liver, renal, and prostate cancer, has been described in PCa fusions but not with itself; however, the fusion of ERG with itself is known to occur in PCa." (PMID 37349736, 2023).